SLC19A3 (solute carrier family 19 member 3)
Diseases named in the same sentence as SLC19A3 in open-access papers (continued):
Sharing a sentence is not in itself a finding about the gene and the disease.
cancer (4 papers, 2011 to 2021). A tumor composed of atypical neoplastic, often pleomorphic cells that invade other tissues. "Here, we aim to develop a new biomarker for cancer diagnosis using methylated SLC19A3 DNA in plasma." (PMID 21789241, 2011). "Here we demonstrate the potential usefulness of methylated SLC19A3 DNA in plasma for cancer detection." (PMID 21789241, 2011). "In the present study, we hypothesized that hypermethylated promoter region of SLC19A3 may serve as a marker for cancer detection." (PMID 21789241, 2011). "Previously, we are the first to report SLC19A3 is epigenetically silenced in human cancers." (PMID 21789241, 2011). "Thus, SLC19A3 might function as a novel candidate tumor suppressor gene in cancers." (PMID 21789241, 2011). "The products of several genes from our potential cell surface list are suspected of playing key roles in more general cancer-related activities such as immunosuppression/evasion (CD14 and CD86), cell migration (ICAM, CDH11) and proliferation (TGFB1, PMEPA1, PDGFRL, SLC19A3)." (PMID 27363029, 2016).
tumor (4 papers, 2011 to 2022). "Our results showed that SLC19A3 mRNA level was significantly decreased in 12 of 15 (80%) breast cancer tumor tissues when compared to their adjacent non-tumor breast tissues (fold change ranging from −2 to −50, P<0.005; Wilcoxon paired test)." (PMID 21789241, 2011). "These genes, such as RFC1, XPO4, THEGL, SLC19A3, TBC1D4, and KCNH5, may have specific functions in metastatic tumour cells." (PMID 34507604, 2021).
mitochondrial disease (3 papers, 2019 to 2025). "Interestingly, the slight upregulation of SLC19A3 (+3.9%) may reflect a compensatory stress response, consistent with prior findings in mitochondrial disease models where SLC19A3 expression is induced under oxidative stress." (PMID 40559423, 2025).
kidney diseases (2 papers, 2021 to 2022). "Other detected genes including SLC19A3, CTF1, and GATM are related to kidney diseases." (PMID 35464862, 2022).
metabolic disease (2 papers, 2021 to 2025). A congenital disorder (due to inherited enzyme abnormality) or acquired (due to failure of a metabolically important organ) disorder resulting from an abnormal metabolic process. "Our results suggest a connection between selected SLC19A3 variants and the severity of metabolic diseases or their response to treatment." (PMID 40243602, 2025). "Thiamine metabolism dysfunction syndrome 2 (THMD2) is a rare metabolic disorder caused by SLC19A3 mutations, inherited in autosomal recessive pattern." (PMID 34276785, 2021).
brain disorder (1 paper, 2020). A disease affecting the brain or part of the brain. "This breed-specific fatal brain disorder in Alaskan huskies is associated with a deleterious loss-of-function variant in SLC19A3 encoding for a thiamine transporter 2 (THTR2) with a predominately central nervous system (CNS) distribution." (PMID 33081289, 2020).
neurological diseases (1 paper, 2014). "Four patients suffering SLC19A3 mutations had no relevant family history for neurological diseases and were normally developing children until the onset of symptoms (mean age 3 years, range 1 month - 8 years)." (PMID 24957181, 2014).
SLC19A3 also shares sentences with these, for which no sentence is quoted: epilepsy (4 papers); developmental delay (2); megaloblastic anemia (2); microcephaly (2); movement disorder (2); alcohol dependence (1); alpha-mannosidosis (1); Alzheimer disease (1); Ataxia (1); autism (1); bacterial infection (1); biotinidase deficiency (1); Brain atrophy (1); Cerebral cortical atrophy (1); cervical cancer (1); chronic kidney disease (1); colitis (1); dermatomyositis (1); diabetic nephropathy (1); ependymoma (1); Epileptic spasm (1); External ophthalmoplegia (1); Failure to thrive (1); folate deficiency (1); generalized dystonia (1); genetic disorder (1); glycogen storage diseases (1); Hyperglycemia (1); Infantile encephalopathy (1); infection (1).
A further 15 diseases each share a sentence with SLC19A3 in 1 paper.